MSLN (mesothelin)
Diseases named in the same sentence as MSLN in open-access papers (continued):
Sharing a sentence is not in itself a finding about the gene and the disease.
ovarian carcinoma (continued). "Next, the therapeutic effects of anti-MSLN on ovarian cancer growth and metastasis were estimated in vivo." (PMID 33613114, 2021). "enrolled five patients with mesothelin expressing recurrent ovarian cancer in a phase I study (NCT02159716)." (PMID 34386017, 2021). "As regards mesothelioma, the same positive results seen in ovarian cancer (see Section 7) using HSP70 fused to an antibody fragment directed at mesothelin were also observed in malignant mesothelioma-bearing mice." (PMID 32635668, 2020). "Consistent with the in vitro results, we demonstrated that elevated levels of MSLN enhances tumor burden, invasion and dissemination of ovarian cancer cells when intraperitoneally injected into nude mice." (PMID 32612258, 2020). "A number of agents including CAR T-cells targeting MSLN have been developed, and are currently in phase I and II clinical trials for ovarian cancer." (PMID 32937961, 2020). "The successful tumor delivery of mesothelin-targeted imaging agents utilizing full monoclonal antibodies has been reported in patients with mesothelioma, ovarian cancer and PDAC, providing proof that MSLN-targeting can result in tumor-specific delivery." (PMID 32605175, 2020). "Recently, the NKG2D transmembrane domain has been combined with an anti-mesothelin scFv and the NK cell-specific signaling domain 2B4 and CD3ζ to target ovarian cancers." (PMID 33391277, 2020). "Then, we selected three MSLNhigh (OVCAR3, OVCAR8, and Kuramochi) and two MSLNlow (OVCAR4 and BG1) ovarian cancer cell lines to generate MSLN knockout (ΔMSLN) and constitutively MSLN overexpression (MSLN OE) cells, respectively." (PMID 32612258, 2020). "Collectively, these results indicate that MSLN expression triggers increased tumor burden and dissemination of ovarian cancer cells in vivo." (PMID 32612258, 2020). "The results obtained from our in vitro studies suggest that MSLN contributes to the metastatic potential of ovarian cancer cells by regulating anoikis resistance, anchorage-independent cell growth, invasion and mesothelial clearance." (PMID 32612258, 2020). "It is important to note here that anti-MSLN antibodies have frequently been identified to be present in blood samples of patients with mesothelioma and ovarian cancers, thereby advocating MSLN as a valuable immunogenic protein." (PMID 32517181, 2020). "Initially, MSLN expression has been reported in 90% of mesothelioma and in 60 to 65% of ovarian cancers samples by Pastan’s team." (PMID 32517181, 2020). "Here, we identified mesothelin (MSLN) as a crucial protein in the multistep process of peritoneal dissemination of ovarian cancer." (PMID 32612258, 2020). "Collectively, these results provide strong evidences that MSLN is a key player in the multistep process of peritoneal dissemination in ovarian cancer." (PMID 32612258, 2020). "To determine the role of MSLN in ovarian cancer cell invasion we used single and aggregate cell invasion assays." (PMID 32612258, 2020). "Mucin 16, α-folate receptor, and mesothelin are being investigated as specific targets of genetic modification of chimeric antigen receptor T (CAR-T) cell therapies for ovarian cancer." (PMID 33123161, 2020). "Overexpression of MSLN in 86% of metastatic tissues derived from ovarian cancers suggests its implication in the metastatic process." (PMID 32517181, 2020). "There are also a number of clinical trials currently underway which include ovarian cancer patients with anti-MSLN CAR-T cells." (PMID 32937961, 2020). "This junction occurs in an antisense transcript of MSLN, which codes for a protein known to bind to the well-known ovarian cancer biomarker MUC16 (CA125)." (PMID 34316681, 2020). "In one translational clinical study in women with ovarian cancer, a median blood serum level of mesothelin was 17 ng mL−1 (range: 0–52 ng mL−1)." (PMID 32764223, 2020).
ovarian carcinoma (continued). "In a single center, single arm, open label clinical trial (NCT03692637), mesothelin-positive patients with stage II-IV epithelial ovarian cancer will receive autologous NK cells engineered to express an anti-mesothelin CAR." (PMID 32751977, 2020). "Our in vitro findings jointly indicate that MSLN contributes to the metastatic potential of ovarian cancer cells by regulating anoikis resistance, anchorage independent cell growth, invasion and mesothelial clearance." (PMID 32612258, 2020). "In order to setup an experimental model, we studied MSLN expression in eleven ovarian cancer cell lines, two human fallopian tube secretory epithelial cell lines and one human ovarian surface epithelial cell line." (PMID 32612258, 2020). "A dual-CAR approach targeting CD24 and MSLN with engineered NK cells has been tested in vitro against ovarian cancer cell lines and patient-derived primary tumour samples with promising results." (PMID 32937961, 2020). "To mimic this process, we used an aggregate cell invasion assay and have shown that MSLN levels regulate the invasive capacity of ovarian cancer cells." (PMID 32612258, 2020). "We first conducted a search on MSLN expression and clinical impact on cancer in general, and ovarian cancer in particular." (PMID 32612258, 2020). "The presented study supports the rationale for combining the MSLN-TTCs with DDR inhibitors based on their individual mode of action as a new strategy for treating ovarian cancer characterized by overexpression of MSLN." (PMID 30850485, 2019). "As a large, heavily glycosylated molecule, MUC16 extends from the surface of ovarian cancer cells and binds to mesothelin, a protein that is found on the surface of mesothelial cells lining the peritoneum." (PMID 31514468, 2019). "The interaction of CA125 and MSLN play an important role in ovarian cancer cell peritoneal implantation and increase the motility and invasion of pancreatic carcinoma cells." (PMID 31463062, 2019). "Analogous to mesothelioma and ovarian carcinoma, a significant increase of MSLN was detected in plasma from patients with hydrosalpinx." (PMID 31222072, 2019). "The expression pattern of MSLN provides an exciting opportunity for its use in targeted therapy in various types of malignant tumors, including pancreatic cancer, ovarian cancer, lung cancer, TNBC and gastric cancer." (PMID 31463062, 2019). "The elevated expression of MSLN was correlated with poorer prognoses in patients with ovarian cancer, cholangiocarcinoma, lung adenocarcinoma, triple negative breast cancer and resectable pancreatic adenocarcinoma." (PMID 31463062, 2019). "MSLN was first described as a membrane protein expressed on mesothelioma and ovarian cancer cells and normal mesothelial cells." (PMID 31463062, 2019). "Analogues to ovarian cancer we also observed a significant increase of MSLN in plasma from patients with hydrosalpinx." (PMID 31222072, 2019). "Mesothelin is a tumor antigen that is highly expressed on the surface of common epithelial cancers including ovarian cancer." (PMID 31320999, 2019). "Clarifying the function of MSLN will enhance its clinical application in ovarian cancer, including early detection, chemo-response, prognosis and therapeutic targeting." (PMID 30134520, 2018). "For example, they found low levels of certain markers that have been gaining traction as drug targets (EphA2), or that have been touted as specific for (MUC16 and FOLR1) or overabundant (Mesothelin) in ovarian cancer." (PMID 30011875, 2018). "In contrast, MSLN is highly expressed in human cancers including 70% of ovarian cancers, mesotheliomas, and pancreatic adenocarcinoma and therefore identified as a tumor-associated marker." (PMID 30134520, 2018). "Chang K, and Pastan I. Molecular cloning of mesothelin, a differentiation antigen present on mesothelium, mesotheliomas, and ovarian cancers." (PMID 30400822, 2018).
ovarian carcinoma (continued). "In epithelial ovarian cancer, high mesothelin expression has been shown to correlate with chemoresistance and poor prognosis." (PMID 30344925, 2018). "Mesothelin has been shown to be overexpressed in many human cancers, including mesothelioma, ovarian cancer, pancreatic cancer, lung cancer, gastric cancer, and biliary cancer." (PMID 30140382, 2018). "Enhanced expression of MMP-7, also known as matrilysin, in response to IL-8 and VEGF in ovarian cancer cells promotes invasion and metastasis of ovarian cancer through mesothelin (MSLN) activated MAPK/ERK and Janus kinase (JNK) pathways." (PMID 29393911, 2018). "After initial attachment of ovarian cancer cells to the peritoneal mesothelium, the co-overexpression of both MSLN and CA125 can lead to recruitment of other ovarian cancer cells being sloughed off from the primary site." (PMID 30134520, 2018). "Conversely, MSLN has been shown to bind to the ovarian cancer antigen, CA-125, and thought to play a role in the peritoneal diffusion of ovarian tumor cells." (PMID 30134520, 2018). "Mesothelin is highly expressed on the surface of tumor cells in various cancers, including ovarian cancer, whereas in normal tissue mesothelin shows limited expression." (PMID 30344925, 2018). "Anetumab ravtansine showed potent antitumor activity as a monotherapy in ovarian cancer models with high mesothelin expression." (PMID 30344925, 2018). "Mesothelin (Msln) is a rational target for ovarian cancer immunotherapy - it contributes to the malignant and invasive phenotype in these tumors and has limited expression in healthy cells." (PMID 30400822, 2018). "Specifically, MSLN has been shown to have oncogenic properties by increasing ovarian cancer invasion by inducing MMP-7 through MAPK/ERK and JNK pathways and by inducing drug resistance through PI3K/AKT and MAPK/ERK signaling pathways." (PMID 30134520, 2018). "One attractive tumor target is mesothelin (MSLN), a membranous glycoprotein expressed in a variety of cancers, including mesothelioma, ovarian cancer and pancreatic cancer." (PMID 30558663, 2018). "Mesothelin is reported to be highly expressed in several types of malignant tumors, such as malignant mesothelioma, ovarian cancer, pancreatic adenocarcinoma, and lung adenocarcinoma." (PMID 28460459, 2017). "Both a-folate receptor (FRa) (90%) and mesothelin (70%) were overexpressed in ovarian cancers, and their expression pattern on normal tissues is mainly non-overlapping." (PMID 28356156, 2017). "MMP-7 also promotes the invasion and metastasis of ovarian cancer through mesothelin (MSLN)-activated MAPK/ERK and JNK pathways." (PMID 28538838, 2017). "Mesothelin is a 40 kDa tumor differentiation antigen present on normal mesothelial cells, but overexpressed in mesothelioma, meningioma, ovarian cancer, lung cancer and pancreatic adenocarcinomas." (PMID 29113296, 2017). "Mesothelin enhances ovarian cancer invasion by MMP-7 expression through the MAPK (mitogen-activated protein kinase)/ERK (extracellular-signal-regulated kinase) and JNK (c-Jun N-terminal kinase) signal transduction pathways." (PMID 28538838, 2017). "TEAD1/2 enhanced mesothelin transcription which was frequently overexpressed in pancreatic and ovarian cancer." (PMID 29050244, 2017). "In fact, we have successfully identified a targeted adenovirus to mesothelin, a surface glycoprotein overexpressed in pancreatic cancer, ovarian cancer and malignant mesothelioma." (PMID 29100290, 2017). "Tumor uptake of 89Zr-MMOT0530A was correlated with MSLN expression levels determined with IHC scores (6 patients with pancreatic cancer and 4 patients with ovarian cancer)." (PMID 27252651, 2016). "Ovarian cancer patient FI1-19 showed CD8+ T-cell responses against all three CT antigens as well as mesothelin in the early post-treatment pool of CD8+ cells and against MAGE-A1 in the late pool." (PMID 26981247, 2016).
ovarian carcinoma (continued). "The differentiation antigen mesothelin was also analysed for patient FI1-19 diagnosed with ovarian cancer." (PMID 26981247, 2016). "Accumulating evidence has shown that MSLN is overexpressed in various cancers, including pancreatic adenocarcinoma, ovarian cancer, and mesothelioma." (PMID 25883990, 2015). "On the contrary, MSLN is widely expressed in human cancers, for example, the majority of ovarian cancers and pancreatic adenocarcinomas, and in 100% of epithelial mesotheliomas." (PMID 25883990, 2015). "For mesothelioma, pancreatic and ovarian cancer, drugs are currently in development that target MSLN." (PMID 26172299, 2015). "This does not account for all tumors, as 50–88% of ovarian cancers are considered MSLN positive based on IHC, while with our technique we find 66% of ovarian cancer samples having a predicted MSLN amplification." (PMID 26172299, 2015). "MSLN was found as an antigen recognized by the monoclonal antibody (mAb), K1, generated by immunization of mice with the human ovarian carcinoma cell line, OVCAR-3." (PMID 25883990, 2015). "In ovarian cancer 66% of 1,255 tumors had a predicted MSLN amplification and in cervical cancers (N = 114) this was 20%." (PMID 26172299, 2015). "Immunohistochemistry studies have shown that mesothelin is expressed in virtually all mesotheliomas and pancreatic ductal adenocarcinomas, a high percentage of epithelial ovarian cancers, and non-small cell carcinomas of the lung." (PMID 25502863, 2015). "Studies with immunohistochemical (IHC) analyses showed high MSLN expression in 100% of the epithelial mesotheliomas, 90–100% of pancreatic and 66–100% of ovarian cancers." (PMID 26172299, 2015). "Vectors using murine mesothelin in an immune competent mouse model with a native ovarian cancer are under development and will allow in vivo testing of the vaccine with these immune modulators." (PMID 25933160, 2015). "Previously, we and others have shown that the serum N-ERC/mesothelin level is useful for diagnosing human mesothelioma and ovarian cancer." (PMID 24146039, 2014). "We have demonstrated that this bifunctional fusion protein effectively binds BR5FVB1 ovarian cancer cells or 40L mesothelioma cells through the interaction of scFv with MSLN on the surface of tumor cells." (PMID 24565018, 2014). "We evaluated the therapeutic efficacy of this MSLN-targeted fusion protein in syngeneic mouse models of ovarian cancer and mesothelioma and examined its mechanism of action in in vitro and in vivo cross-presentation assay systems." (PMID 24565018, 2014). "In the present work, novel, sensitive electrochemiluminescent assays were developed for the soluble forms of FRA, MSLN and MPF and were evaluated in a large cohort of ovarian cancer patient samples." (PMID 23590973, 2013). "In the resulting model, CA125 and MSLN were shown to increase the probability of a diagnosis of ovarian cancer as their values increased, whereas MPF showed the opposite effect." (PMID 23590973, 2013). "The tumor-homing portion of the therapeutic chimeric protein, an anti-mesothelin single chain variable fragment (meso-scFv), had high binding affinity to mesothelin, which is overexpressed by most ovarian cancers." (PMID 24354786, 2013). "In this work, we studied the effects of silencing MSLN on viability, invasiveness and cell signaling pathways in cancer cells derived from mesothelioma, pancreatic and ovarian cancer." (PMID 22485139, 2012). "Some investigators have reported that mesothelin can be a new marker for the diagnosis of ovarian carcinoma and as a target in mesothelin-expressing tumours, including pancreatic cancer." (PMID 23034174, 2012). "MSLN is also upregulated in other cancers including ovarian cancer, and pancreatic ductal adenocarcinoma and in its original description, soluble mesothelin was found to be a serum marker for ovarian cancer." (PMID 21984916, 2011).
ovarian carcinoma (continued). "Evidence suggests that MSLN confers resistance to anoikis in breast cancer and chemotherapy (platinum + cyclophosphamide/paclitaxel) in ovarian cancer." (PMID 21880146, 2011). "Our findings show that mesothelin gene and protein expression are elevated in chicken ovarian tumors and the results further validate the laying hen as an animal model for human ovarian cancer." (PMID 21801396, 2011). "We also modeled functional interactions between macrophages and soluble mesothelin using an in vitro system of co-culture in transwells of healthy donor macrophages with human ovarian cancer cell lines." (PMID 22163010, 2011). "To address this question, we analyzed the binding of tumor-released mesothelin to ascites-infiltrating macrophages from ovarian cancer patients." (PMID 22163010, 2011). "MSLN-induced Mcl-1 upregulation has been reported in taxol resistant ovarian cancer cells indicating its importance in MSLN induced protection from various apoptotic stimuli." (PMID 21880146, 2011). "The frequently elevated expression of mesothelin in cancer cells compared to normal cells and the immune response to mesothelin have led to exploration of mesothelin as a therapeutic target for ovarian cancers." (PMID 21801396, 2011). "The increased tissue expression and the presence of circulating mesothelin in human ovarian cancer is relatively specific and mesothelin shows promise as a specific marker and a target of immunotherapy for ovarian cancer." (PMID 21801396, 2011). "Circulating mesothelin is a relatively specific marker for human ovarian cancer and autoantibodies to mesothelin were reported." (PMID 21801396, 2011). "Previous studies showed that mesothelin protein frequently is expressed in human ovarian carcinomas and although there are some differences among studies, mesothelin is predominantly expressed in serous tumors, similar to the findings of this study." (PMID 21801396, 2011). "An important study published recently has concluded that a steady increase in the serum concentrations of CA125, HE4, and mesothelin can be detected in patients up to 1-3 years before a clinical diagnosis of ovarian cancer is made in patients." (PMID 20350313, 2010). "Some investigators have reported that mesothelin can be a new marker for the diagnosis of ovarian carcinoma and as a target in mesothelin-expressing tumours." (PMID 19293794, 2009). "Recently, several molecules other than mesothelin have been found to be potential biomarkers for ovarian carcinoma, such as DF3, vascular endothelial growth factor, MUC1, HE4, and CA19-9." (PMID 19293794, 2009). "Mesothelin is elevated in the serum of 76% ovarian cancer patients and kallikrein 10 is elevated in 56% of ovarian cancer patients." (PMID 15199385, 2004). "Overall, MSLN(+)CTCis promising biomarker for both the diagnosis and treatment of ovarian cancer." (PMID 40792273, 2025). "Mesothelin is another target highly expressed in ovarian cancer." (PMID 41211166, 2025). "A phase 1 clinical trial (NCT03198546) evaluating CAR-T cells with constitutive expression of IL-7 and CCL19 in six patients with progressive hepatocellular carcinoma, pancreatic carcinoma, and ovarian carcinoma expressing either GPC3 or MSLN showed promising results." (PMID 41154636, 2025). "MSLN functions as a glycoprotein on the cell surface, which is widely expressed in tumors such as malignant pleural mesothelioma, pancreatic cancer, ovarian cancer, some lung cancer and so on." (PMID 40849468, 2025). "Additionally, we performed immunohistochemical analysis on clinical specimens, including 10 epithelial ovarian cancer tissue samples and 5 normal ovarian surface epithelial tissue samples, to examine MSLN and EpCAM expression patterns in tissue contexts." (PMID 40792273, 2025). "MSLN is overexpressed in ovarian cancer, making it an ideal target for immunotherapy." (PMID 40705122, 2025). "Mesothelin (MSLN) is a target with increased expression in ovarian cancer." (PMID 40722601, 2025).